OR10A5 (olfactory receptor family 10 subfamily A member 5)
Description:
Odorant receptor (Potential). May be involved in taste perception.
Synonyms: OR11-403; OR10A1; JCG6
Tractability: Small molecule: it belongs to a druggable protein family. Antibody: UniProt places it where antibodies can reach, with medium confidence; UniProt predicts a signal peptide or a membrane-spanning region; its Gene Ontology location is reachable by antibodies, with medium confidence.
Gene: Protein-coding gene on chromosome 11 (6,845,683 to 6,846,636, forward strand). Ensembl gene ENSG00000166363.
Subcellular location: Cell membrane
Pathways (Reactome):
Sensory Perception: Expression and translocation of olfactory receptors
Gene Ontology:
Molecular function: olfactory receptor activity; G protein-coupled receptor activity
Biological process: detection of chemical stimulus involved in sensory perception of smell; sensory perception of smell; G protein-coupled receptor signaling pathway
Cellular component: membrane; plasma membrane
Genetic constraint (gnomAD): Loss-of-function variants: 9 observed, 10.95 expected, observed/expected ratio (o/e) 0.82, 90% interval 0.49 to 1.43. The upper end of that interval is the gene's LOEUF score, 1.43, which puts it in group 5 of 6, group 1 being the genes least tolerant of losing a copy. Missense variants: 353 observed, 371.88 expected, observed/expected ratio (o/e) 0.95, 90% interval 0.87 to 1.04. Synonymous variants: 143 observed, 147.08 expected, observed/expected ratio (o/e) 0.97, 90% interval 0.85 to 1.12.
Homologues: Orthologues: chimpanzee OR10A5 (99% identical), dog OR10A5F (93% identical), dog OR10A5 (92% identical), mouse Or10a5 (92% identical), dog OR10A5E (92% identical), rat Or10a5 (90% identical), dog OR10A5D (89% identical), mouse Or10a2 (89% identical), rat Or10a2 (88% identical). Paralogues in human: OR10A2 (91% identical), OR10A4 (73% identical), OR10A7 (60% identical), OR10A3 (57% identical), OR10A6 (54% identical), OR10C1 (51% identical), OR10P1 (48% identical), OR10H5 (47% identical), OR10AG1 (47% identical), OR2C3 (47% identical), OR10H1 (47% identical), OR10H2 (46% identical), and 80 more.
Diseases named in the same sentence as OR10A5 in open-access papers:
OR10A5 is named in the same sentence as 1 disease in open-access papers, as found by Europe PMC text mining. Sharing a sentence is not in itself a finding about the gene and the disease.
OR10A5 shares sentences with these, for which no sentence is quoted: cancer (1 paper).